CHAT (choline O-acetyltransferase)
Diseases named in the same sentence as CHAT in open-access papers (continued):
Sharing a sentence is not in itself a finding about the gene and the disease.
tumor (14 papers, 2015 to 2025). "The result showed that ChAT knockout caused slow tumor relapse, and this effect was rescued through injection of exogenous ACh." (PMID 36048538, 2022). "Correlation of ChAT expression levels to tumor stage revealed that high expression levels ChAT were indeed associated with low tumor stages (r2: 0.20, p = 0.049)." (PMID 33357230, 2020). "We additionally observed dense ChAT+VAChT+ puncta at sites of neuron-tumor contacts, supporting the existence of synaptic contacts." (PMID 40541171, 2025). "Collectively, our study supports a model whereby tumor antigens induce the expansion of ChAT-expressing Treg cells and PD-1+ Tconv cells." (PMID 37640929, 2023). "The clonal expansion of ChAT-expressing Treg cells and PD-1+ Tconv cells in our model appears to be driven by tumor antigens." (PMID 37640929, 2023). "We postulate that this clonal divergence in ChAT expression likely reflects the complexity of the tumor microenvironment." (PMID 37640929, 2023). "To determine the role of tumor antigens in the induction of ChAT-expressing T cells, we crossed Chat-GFP mice with chicken ovalbumin (OVA)-specific TCR transgenic OT-II mice." (PMID 37640929, 2023). "We also found that both the transcriptional and protein levels of ChAT and VAChT, which play pivotal roles in the synthesis and transportation of ACh respectively, were also elevated in the lungs of tumor-bearing mice with chronic stress." (PMID 37773152, 2023). "To determine the clinical relevance of the key regulators ChAT and AChE in ACh metabolism, we performed immunohistochemical analysis on 20 paired tumor biopsies taken before and after EGFR-TKI therapy." (PMID 36048538, 2022). "EA leads to c-Fos expressions in ChAT-positive neurons in the dorsal motor nucleus of the vagus, and these ameliorating effects of EA on tumor growth were abolished by subdiaphragmatic VGX." (PMID 35095910, 2021). "For instance, the methylation levels of CDCA2 and CHAT were found to be approximately 20 times higher in the tumor group than that in the control group." (PMID 35126463, 2021). "RT-PCR was performed to determine the ChAT and ChoK mRNA expression in the tumor and normal tissues." (PMID 25591716, 2015). "Additionally, plasma ACh levels and tumor ChAT expression highly correlated with response to EGFR-TKI and progression-free survival in human NSCLC patients." (PMID 36048538, 2022). "Notably, to determine the functional role of the short ChAT isoform in vivo, we established the PC9 xenograft models and found that short ChAT isoform overexpression enhanced drug tolerance and further led to a more rapid tumor relapse." (PMID 36048538, 2022). "Importantly, plasma ACh levels and tumor ChAT expression of human patients with NSCLC correlated with response to EGFR-TKI treatment and progression-free survival." (PMID 36048538, 2022). "In addition, with long-term osimertinib treatment, ChAT knockout significantly enhanced drug response and inhibited tumor relapse, and improved survival outcome." (PMID 36048538, 2022). "Taken together, these findings demonstrated that the ACh/ChAT increase was, at least in part, an adaptive response upon EGFR-TKI treatment, although we could not exclude the possibility of intrinsically high levels of the short ChAT isoform in tumor cells." (PMID 36048538, 2022). "Hence, we concluded that advanced tumor stages were characterized by low cholinergic input due to low ChAT expression, and yet also by suppression of the degrading enzyme AChE." (PMID 33357230, 2020). "Additionally, we sought to determine whether ChAT is localized extracellularly as a membrane-anchored enzyme in these tumor cells, as we previously observed in human spermatozoa." (PMID 41226363, 2025). "Histologically, ChAT–GFP+Foxp3+ Treg cells and ChAT–GFP+ Tconv cells accumulated in HCC tissue, in particular at the tumor border, and were also present in immune cell clusters associated with neoplastic hepatocytes." (PMID 37640929, 2023).
tumor (continued). "Taken together, these data confirm that tumor antigens can induce ChAT-expressing Treg cells and PD-1+ Tconv cells and demonstrate that the expansion of ChAT-expressing T cells in liver cancer depends on TCR activation by tumor antigens." (PMID 37640929, 2023). "It was speculated that the possible mechanism involved in the attenuation of tumor growth by the 4-DAMP treatment could be through the inhibition of immunosuppressive (PD-L1) and cholinergic (M3R and ChAT) markers." (PMID 36614038, 2022). "A ChAT increase may serve as an indicator that the TKI is initially effective in inhibiting EGFR, which may also indicate residual disease formation and the origin of tumor recurrence at a late stage." (PMID 36048538, 2022). "Moreover, we also found the expression of short ChAT isoform at mRNA and protein levels in tumor and adjacent normal lung tissues derived from NSCLC patients with or without EGFR mutation." (PMID 36048538, 2022). "Meanwhile, while immunohistochemical detection of choline acetyltransferase (CHAT) has been reported in HN-PG31, CHAT mRNA was not overexpressed in these tumours." (PMID 40097403, 2025). "However, three out of the 18 tumors exhibited no expression of ChAT and ChoK, but exhibited a high uptake of 11C-Choline, which may be due to other factors, including high expression of nAChR, the oxidation pathway or tumor blood flow." (PMID 25591716, 2015).
cancer (8 papers, 2012 to 2025). A tumor composed of atypical neoplastic, often pleomorphic cells that invade other tissues. "Clarifying the localization and membrane association of ChAT is essential for understanding the mechanism of in situ ACh signaling and its potential role in cancer cell survival, communication, and therapeutic targeting." (PMID 41226363, 2025). "Thus, the use of hNGF1–14 peptides to sustain BDNF and ChAT levels is of interest for several human diseases associated to cholinergic disturbances, like AD, PD, DS and cancer." (PMID 32024191, 2020). "Moreover, the presence of key components of the cholinergic system—including its central enzyme, ChAT—raises the possibility of a significant role for cholinergic signaling in cancer cell biology." (PMID 41226363, 2025). "Such PET tracer may also be useful for diagnosis of the certain type of cancer tumors, where ChAT is overexpressed." (PMID 29176551, 2017). "The availability of a potent and specific ChAT radiotracer can be of significant interest in elucidating the functional role of this enzyme in the brain as well as in the peripheral system specifically related to cholinergic signaling in anti-inflammatory pathways and cancer biology." (PMID 29176551, 2017). "In light of these findings, the potent ChAT inhibitors identified in our study might also be developed as potential therapeutic candidates for the prevention and treatment of different forms of cancer." (PMID 29176551, 2017). "While only four cancer cell lines were analyzed, our findings suggest that extracellular ChAT localization is not a general feature of cancer cells." (PMID 41226363, 2025). "The studies indicate that the cancer cells by upregulating ChAT may increase the synthesis of non-neuronal ACh, which act as an autocrine agent." (PMID 29176551, 2017). "All tuft cell-like cancers identified in this way also strongly expressed other tuft cell-markers, such as TRPM5, SOX9, ASCL2, and AVIL but not CHAT." (PMID 36402755, 2022).
bacterial infection (3 papers, 2023 to 2024). "Using Chat-GFP reporter mice, we observed marked upregulation of ChAT in monocyte-derived small peritoneal Mφs (SmPMs) in response to Toll-like receptor agonists and bacterial infections." (PMID 38923993, 2024). "However, there is also increasing evidence that ACh release by ChAT-expressing haematopoietic and stromal cells plays roles in fighting bacterial infection and promoting epithelial barrier formation in the gut." (PMID 38500783, 2024). "Conversely, overexpression of ChAT promoted survival after bacterial infection." (PMID 38063293, 2023). "SmPMs but not LaPMs are the predominant peritoneal Mφ population that express ChAT in response to TLR agonists and bacterial infection." (PMID 38923993, 2024).
psychiatric disorder (3 papers, 2018 to 2025). A disorder characterized by behavioral and/or psychological abnormalities, often accompanied by physical symptoms. "Compared to controls, only ChAT levels were significantly reduced, highlighting that cholinergic dysfunction may underlie both cognitive and non-cognitive behavioral symptoms across a range of neurological and psychiatric disorders." (PMID 41322300, 2025). "However, the LHb has received considerable attention for its potential role in cognition and pathogenesis of various psychiatric disorders, and since we observed eGFP expression in the LHb, the ChAT-eGFP mouse model could be a potential transgenic model to study further on the habenula complex." (PMID 36650430, 2023).
neurological disease (2 papers, 2019 to 2021). "Despite these reports, studies of other neurological disorders suggested significant involvement of CHAT enzyme alternations and described its possible connection to behavioral changes." (PMID 31652960, 2019).
neurodevelopmental disorder (1 paper, 2020). A behavioral and cognitive disorder with onset during the developmental period that involves impaired or aberrant development of intellectual, motor, or social functions. "Of note, reduced ChAT expression deficits occur in several age-related CNS pathologies, like AD and PD and in neurodevelopmental disorders even in absence of neuronal death." (PMID 32024191, 2020).
of the colon (1 paper, 2023). "Choline acetyltransferase (ChAT) and ELOVL fatty acid elongase 1 (ELOVL1) have been implicated in diseases of the colon." (PMID 37569842, 2023).
CHAT also shares sentences with these, for which no sentence is quoted: acute pancreatitis (2 papers); atherosclerosis (2); encephalopathies (2); heart failure (2); multiple sclerosis (2); Rett syndrome (2); acute myocardial infarction (1); adenocarcinoma (1); alcohol use disorder (1); Alpha-thalassemia (1); Apnea (1); asthma (1); Ataxia (1); behavioral disorders (1); bipolar disorder (1); Cataplexy (1); channelopathies (1); cognitive (1); cognitive disorder (1); colorectal cancer (1); Delusion (1); diabetic encephalopathy (1); Down syndrome (1); drug dependence (1); emotional dysregulation (1); epilepsy (1); exfoliation syndrome (1); genetic disorders (1); Glucose intolerance (1); Hyperammonemia (1).
A further 30 diseases each share a sentence with CHAT in 1 paper.